RN7SL388P (RNA, 7SL, cytoplasmic 388, pseudogene)
Gene: Miscellaneous RNA gene on chromosome X (72,198,712 to 72,199,050, forward strand). Ensembl gene ENSG00000239577.
Homologues: Orthologues: chimpanzee Metazoa_SRP (90% identical), macaque Metazoa_SRP (69% identical). Paralogues in human: Metazoa_SRP (69% identical), RN7SL2 (69% identical), RN7SL1 (68% identical), RN7SL3 (68% identical), Metazoa_SRP (68% identical), RN7SL126P (66% identical), RN7SL187P (66% identical), Metazoa_SRP (66% identical), RN7SL444P (66% identical), RN7SL47P (66% identical), RN7SL45P (66% identical), RN7SL464P (66% identical), and 704 more.